RNU6ATAC41P (RNA, U6atac small nuclear 41, pseudogene)
Gene: Small nuclear RNA gene on chromosome 8 (100,739,802 to 100,739,927, reverse strand). Ensembl gene ENSG00000221527.
Homologues: Orthologues: chimpanzee RNU6ATAC41P (100% identical), macaque RNU6ATAC41P (92% identical). Paralogues in human: RNU6ATAC (87% identical), RNU6ATAC21P (85% identical), RNU6ATAC27P (81% identical), RNU6ATAC6P (80% identical), RNU6ATAC8P (80% identical), RNU6ATAC7P (78% identical), RNU6ATAC19P (62% identical), RNU6ATAC39P (52% identical), RNU6ATAC22P (52% identical).